CCL4 (C-C motif chemokine ligand 4)
Diseases named in the same sentence as CCL4 in open-access papers (continued):
Sharing a sentence is not in itself a finding about the gene and the disease.
cancer (continued). "In Nf1OPG mice, we elucidated a “neuron-immune-cancer cell” circuit, where T cells are induced by Nf1-mutant neuron-produced midkine to express Ccl4, which stimulates TAMs to secrete Ccl5, a key growth factor for Nf1-OPG development and progression." (PMID 38308315, 2024). "It is recognized as an important regulatorof cancer progression by repressing expression of key inflammatoryfactors such as interferon-γ and chemokine (C–C motif)ligand 4 (CCL4)." (PMID 38412264, 2024). "The results designated CCL19 as the most promising APC-binding molecule for delivering in silico-predicted cancer neoepitopes, closely followed by CCL4." (PMID 37720215, 2023). "Meanwhile, previous studies uncovered a mechanism for this immune evasion: GABA/GABABR/β-catenin signaling in cancer cells suppresses the expression of pro-inflammatory chemokines CCL4/5." (PMID 37324489, 2023). "SCD1 inhibition enhanced the production of chemokine C-C motif ligand 4 (CCL4) in cancer cells by reducing Wnt/β-catenin signaling." (PMID 37240297, 2023). "CCR5 binds with high- affinity to CCL5, CCL3 (MIP-1a), and CCL4 (MIP-1b) in cancer cell membranes to mediate diverse signaling cascades in response to its ligands." (PMID 37553567, 2023). "Two discovery pan-cancer datasets were used to examine the 4-chemokine signature (CCL4, CCL5, CXCL9, CXCL10; herein referred to as c-Score) as a predictive biomarker for T cell-inflammation and ICI treatment outcomes across different solid tumor types." (PMID 37558751, 2023). "Mechanistically, ID1 interacts with STAT1 to induce its cytoplasmic distribution and inhibits STAT1-mediated SerpinB2 and CCL4 transcription, two secretory factors responsible for cancer stemness inhibition and CD8+ T cell recruitment." (PMID 37996458, 2023). "The inflammatory chemokine (C-C motif) ligand 4 (CCL4) is also important in the pathogenesis and progression of cancer." (PMID 35884919, 2022). "While HLA-I+ cancer cells released key effector cytokines and chemokines, such as CXCL10, CCL4, CCL5, and IFN-γ, HLA-I–deficient cancer cells had a limited release of proinflammatory cytokines." (PMID 35503263, 2022). "Of the CC chemokines, CCL2, CCL4 and CCL5 have all been implicated in cancer development and metastasis formation." (PMID 36241867, 2022). "RT2 Profiler PCR array for cancer related genes also showed upregulation of several other inflammatory genes including IL-6, CCL4, MCP-1, etc.." (PMID 34900746, 2021). "Our data indicate that muscle-derived CXCL1, IL10 and CCL4 are part of the mechanistic link between exercise and the induction of apoptosis in cancer cells." (PMID 34359731, 2021). "Among them, we found that cells from mice bearing TGF-β-stimulated cancer cells specifically produced granulocyte macrophage colony-stimulating factor (GM-CSF) and chemokine (C–C motif) ligand 4 (CCL4), receptors for which are expressed in macrophages." (PMID 33674758, 2021). "For instance, upregulated CCL4 levels exhibit protumorigenic activities in many different types of cancer." (PMID 34884541, 2021). "Chemokine (C-C motif) ligand 4 (CCL4) has diverse effects on different cancer cells through its interaction with its specific receptor, C-C chemokine receptor type 5 (CCR5)." (PMID 34884541, 2021). "A subsequent analysis revealed that cancer cells in a bone cavity produced abundantly a chemokine, CCL4, which attracted type I collagen-expressing α-SMA+ fibroblasts expressing CCR5, a specific receptor for CCL4." (PMID 33050237, 2020). "The increase in the number of immune cells, induced by CCL3 and CCL4, makes these chemokines a potentially important element of cancer immunotherapy." (PMID 33076281, 2020). "The major cellular source of CCL4 in tumors was CD45-negative cells—presumably cancer cells themselves." (PMID 32194569, 2020). "CCL4 also increases the expression of VEGF-C in a cancer cell, which leads to lymphangiogenesis and lymph node metastasis." (PMID 33076281, 2020).
cancer (continued). "After looking through papers, only 4 genes of these prognostic markers have been verified to be relavant with according cancers, including CCL4 in COAD, CACNA2D3 and SMO in ESCA, and IL23R in LUAD." (PMID 31888612, 2019). "CCR5 is a specific high-affinity receptor for CCL4 and plays a major role in cancer development by increasing inflammation and immune cell recruitment." (PMID 29599774, 2018). "The inflammatory chemokine (C–C motif) ligand 4 (CCL4) plays an important role in the pathogenesis and progression of cancer." (PMID 29599774, 2018). "Correlation analysis between RFC4 and checkpoint gene expression in different types of cancers showed a high correlation with immune genes including CCL4, CCL16, HLA family genes, TNFRSF8, TNFRSF14, TNFRSF18, CD70, CD44 (p < 0.05), CD276, CX3CL1 and VGEGFA (p < 0.05)." (PMID 39031628, 2024). "Previous studies from our laboratory have characterized a “neuron-immune-cancer cell” axis, in which neurons elaborate midkine in an activity-dependent manner, which stimulates T cell Ccl4 production to induce TAM (Tmem119+/Iba1+/CD45low/CD11b+ microglia) Ccl5-mediated support of glioma growth." (PMID 38308315, 2024). "CCL4 is a chemokine that promotes cell proliferation, invasion, and migration of cancer." (PMID 37626750, 2023). "Moreover, accumulating evidence showed the significant role of CCL4 in tumorigenesis development and cancer progression by altering the immune cells in the TME." (PMID 38067251, 2023). "Our results showed that cancer susceptibility was not significantly differently exacerbated by the polymorphisms of CCL4 gene at rs10491121 and rs1634507 at the macroscopic level." (PMID 37593100, 2023). "The P value was greater than 0.05 for all models, indicating the absence of an evident relationship of CCL4 gene rs10491121 and rs1634507 polymorphisms with cancer susceptibility." (PMID 37593100, 2023). "CCL5 and CCL4 were specifically expressed in B-0, which activate antigen presentation pathways and PD-L1/PD-1 immune checkpoints in cancer to recover the adverse effect of low CCL5 expression reducing the recruitment efficiency for cells in immune killing cascades (e.g., cDCs and CTLs)." (PMID 36131282, 2022). "ccl4 has been identified as a gene that plays a role in various cancers." (PMID 35463731, 2022). "Elevated levels of pADPr have also been associated with the release of various chemokines, including monocyte chemoattractant protein-1 (MCP-1 or CCL2), eotaxin (CCL11), macrophage inflammatory proteins MIP-1α (CCL3) and MIP-1β (CCL4), all of which are known to promote cancer invasion." (PMID 35585513, 2022). "Therefore, different mechanisms through β-catenin or ER stress are employed for the SCD1 dependent regulation of CCL4 in cancer cells and in CD8+ T cells." (PMID 35793868, 2022). "Similarly, the undifferentiated MPRO cells expressed higher levels of Il-1β, Ccl2, Ccl3, Ccl4, and iNos when cultured in the supernatant of cancer cells compared to SF media." (PMID 33049964, 2020). "On the other hand, CCL3 and CCL4 also have pro-cancer effects." (PMID 33076281, 2020). "Additionally, however, we noted a specific set of genes encoding chemokines and cytokines, namely CCL4, CCL8, CXCL10, CXCL11, IFI44L, IDO1, and IFNG that were upregulated in 9p CNG cancers." (PMID 29212506, 2017). "In contrast, the secreted CCL3/CCL4 could serve as a biomarker of tumors containing a G4 cancer cell type." (PMID 20021671, 2009). "Additionally, CCL4 expression level affects different cancers differently." (PMID 37593100, 2023). "Importantly, AREG has also been shown to contribute to the neoplastic phenotype of human HCC cells (Castillo 2006 Cancer Research) and therefore the CCL4 model could be used to further study the role of AREG in hepatocarcinogenesis." (PMID 20618941, 2010).
cancer (continued). "For instance, in response to cancer cell conditioned media, CAFs upregulate expression of chemokines such as CCL2, which, together with CCL3 and CCL4 can recruit myeloid cells to the TME." (PMID 39743376, 2025). "Above all, majority of studies have shown that elevated CCL4 and MIF play a promoting role in cancer developments and progression." (PMID 40092701, 2025). "TNF-α induced a significant increase in the secretion of chemokines and cytokines from CT26 cancer cells including CCL2, CCL3, CCL4, CCL5 and G-CSF." (PMID 39310770, 2024). "For instance, researchers have utilized a 12-gene expression signature (including CCL2, CCL3, CCL4, CCL5, and others) to assess TLS presence across different cancer types." (PMID 39620224, 2024). "CCL3 and CCL4 can also be produced by MDSC and TAMs themselves, leading to both autocrine and paracrine STAT3 activation and subsequent enhancement of cancer cell proliferation, invasion, and epithelial–mesenchymal transition." (PMID 38108458, 2024). "Among chemokines, especially CCL4, CCL5, CCL8, CXCL9, CXCL10 and CXCL11 were markedly positive correlated with LAMP3 expression in most cancers." (PMID 38146591, 2024). "The CCL4 and CCL5 chemokines play a vital role in various cancer types in terms of metastasis, invasion, and poor clinical disease outcomes." (PMID 38067251, 2023). "PDCD1, TGFB1, CXCL8, CCL3, CCL4, and CCL5 were highly expressed in subTME-IS; CXCL2 and CXCL12 were highly expressed in subTME-ICI, which was consistent among cancer types." (PMID 38002057, 2023). "The combination of HFD plus cancer resulted in increased expression of some cytokines in the OFB (e.g., Ccl2, Ccl4, Cxcr2, Il1b) and decreased expression of others (e.g., Ccr5, Cx3cl1, eNos, Tnfa) as compared to the HFD group alone." (PMID 38264656, 2023). "Chemokine (C-C motif) ligand 4, also known as CCL4 or macrophage inflammatory protein-1 (MIP-1), is essential for the control of the immune response, inflammation, and the development of cancer." (PMID 37373025, 2023). "The c-Score, derived from expression of CCL4, CCL5, CXCL9, and CXCL10, identified subpopulations of tumors across cancer types with hallmarks of T cell-inflammation." (PMID 37558751, 2023). "For example, CCL4 and CCR5 are crucial in atherosclerosis development and in cancer development and immune system execution." (PMID 37593100, 2023). "To this aim, we measured CCL2, CCL3, CCL4, and CCL5 by CBA in TCM from different cancer types or in cultures of BM cells stimulated with the same TCMs or with recombinant cytokines involved in MDSC differentiation." (PMID 35064009, 2022). "We observed that immunostimulatory chemokines such as CXCL9, CXCL10, CXCL11, CCL4, and CCL5 were consistently down‐regulated for the tumors with high Hh activity across the 14 cancer types." (PMID 34841742, 2022). "The CCL4/CCR5 axis, CXCL9/CXCR3-axis, and CXCL13/CXCR5-axis have previously been shown to promote cancer progression and metastasis." (PMID 36163179, 2022). "After performing the non-parametric U Mann–Whitney test comparing the concentrations obtained in both groups, we observed that the levels of CCL2, CCL4, CEA, and CRP in the entire cancer group were significantly higher (in all cases p < 0.05)." (PMID 35407400, 2022). "In this way, CCL3 (also known as macrophage inflammatory protein-1α, i.e., MIP-1α) and CCL4 (MIP-1β) are pro-inflammatory chemokines that display both pro-and anti-cancer properties." (PMID 35406791, 2022). "In contrast to cancer cells, SCD1 inhibited the production of CCL4 by CD8+ T cells through increased ATF3 activated by ER stress." (PMID 35793868, 2022). "M2 macrophages (C6-Mye) were predicted to secrete the factors CXCL12 and CCL4 to attract CD8+ Tex cells by binding to CXCR3/CXCR4 and CCR5 on CD8+ Tex cells, which are known to recruit immunocytes into cancer tissues." (PMID 35562760, 2022).
cancer (continued). "MANOVA on these genes reveals that this combined set of 7 genes (MYC, CD40LG, CCL4, IL7, TCF4, CCR7 and FASLG) is together statistically significantly reliant on both time post-exposure (p = 0.042) and cancer type (p < 0.001)." (PMID 33941218, 2021). "Together with CCL5/RANTES and CCL4/MIP-1β, RNS, IL-10, and TGF-β promote the recruitment and the immunosuppressive activity of Tregs, at least in cancer and in neonates." (PMID 30873175, 2019). "Although several chemokines, such as CCL4, CCL19, CCL21, CXCL2 or CXCL12, were upregulated at the invasive border than cancer centre, expressions of their receptors were very low in PTC, except for CXCL12 receptor." (PMID 28489070, 2017). "Regardless of clinicopathological characteristics, significant expression differences were observed, including 10 upregulated genes (CCL4/18, CXCL1/10/11, IFNγ, IL2/6/12A, VEGFA) and 1 downregulated gene (HLA-A) in lymphocytes from malignant ascites." (PMID 28620375, 2017). "While Ponader and co-workers have reported that ibrutinib decreases secretion of CCL3 and CCL4 in CLL cells, the cancer cell-autonomous survival function of these chemokines is yet to be explored." (PMID 28036258, 2017). "As a result, SFV-infected cancer cells significantly altered cytokine and chemokine profiles, reducing immunosuppressive factors (e.g., IL-10) and increasing inflammatory mediators (e.g., CXCL10 and CCL4)." (PMID 40547518, 2025). "For example, CCR5 antagonists are already used to treat HIV and some cancers and could be repurposed or developed as a treatment for CAD by inhibiting the effects of CCL4." (PMID 39512689, 2024). "Targeting the CCL4 and CCL5 pathways may offer new strategies for controlling cancer metastasis and improving treatment outcomes in TSCC." (PMID 38067251, 2023). "While the cancer presence alone did not elicit gene expression changes in these adipose tissues, there was a significant increase in Ccl4 (in pmWAT only), Ccl2 and Il6 in both WATs in the HFD/MOSETICv group." (PMID 38264656, 2023). "Interestingly, variations of myeloid chemokine-secreting TANs were identified in all four cancers including two types identified in gastric cancer (tsNeu3 and tsNeu4), NSCLC (TAN-3) and HCC (CCL4+), all of which have elevated levels of myeloid chemokines." (PMID 37534829, 2023). "Given our current understanding of neutrophil heterogeneity across multiple cancers, therapies that expand intratumoural MMP8+ and APOA2+ TANs whilst supressing IFIT1+, SPP1+ and CCL4+ TANs may be effective in improving immunotherapy responses in HCC." (PMID 37534829, 2023). "As with TCGA Pan-Cancer Atlas data, patients with below-median PI24 scores expressed high levels of immunoglobulin genes, CD8A, and chemokine genes (CCL4, CCL5, and CXCL10), and had significantly higher PFS and OS rates (P = 0.00041 and P = 0.0011, respectively)." (PMID 36099049, 2022). "As a seven-transmembrane G protein-coupled receptor, CCR5 can bind to a variety of ligands CCL3 (MIP1α), CCL3L1, CCL4 (MP-1β), CCL5 (RANTES), CCL8 (MCP2), CCL11 (Eotaxin), CCL13 (MCP-4), and CCL16, which are reported to be highly expressed in most malignant tumors." (PMID 36167571, 2022). "Importantly, HLA-I+ cancer cells secreted sustained levels of the chemotactic factors CXCL10, CCL4, CCL5, and IFN-γ cytokine in contrast to the HLA-I– cancer cells." (PMID 35503263, 2022). "According to the literature, CXCL1, IL10 and CCL4 are more or less well described myokines, but as muscle-derived factors no significant anti-cancer effect has been attributed to them yet." (PMID 34359731, 2021). "We propose that muscle-derived IL10, CXCL1 and CCL4 are, at least in part, responsible for the exercise-mediated upregulation of CASP3 and 7 gene expression and consequently their increased protein levels in PC and other cancer cells." (PMID 34359731, 2021).
cancer (continued). "Similarly, another study found that tumor cell debris, after cancer therapy, promotes survival and growth of living cancer cells in multiple tumors through the secretion of pro-inflammatory cytokines such as TNF-α, IL-6, IL-8, CCL4, and CCL5 by macrophages." (PMID 32326073, 2020). "For example, while neither (mf or cancer cell lines) induces the production of CCL4, TNF-α, IL-10, or VEGF, they both significantly enhance the production of IP-10 and CCL22 in human monocytes." (PMID 29668679, 2018). "We found that overexpression of EBNA2 and its targets, CCL3 and CCL4, led to doxorubicin resistance, independent of the pathway underlying LMP1-mediated protection of cancer cells against chemotherapeutic agents." (PMID 28036258, 2017). "Surprisingly, in that study in patients at stages 1–3 with elevated CCL4 levels, the malignant tumor did not reoccur after radical surgery." (PMID 25401103, 2014). "Besides, the presence of CCL4 in NK cells, along with its receptor SLC7A1 in cancer cells, and CCR8 in CD4 + naïve T cells/Treg cells signified an activation of NK cells, which may predict a more favorable pathological response in pCR patients before NAT." (PMID 38566201, 2024). "Since there is discrepancy regarding the anti-cancer impact of CXCL1 and CCL4 between our results and some data from the literature, it is of interest whether the site of expression determines different biological functions of CXCL1 and CCL4." (PMID 34359731, 2021). "However, its only unique inverse correlation with C-C motif chemokine ligand 4 (CCL4) relates to the protective effect of lycopene on oxidative stress-induced cellular damage and implicates a potential role in chemoprotection in cancer or other diseases." (PMID 28194237, 2017). "However, neither GB60 nor CCL4 have genetic alterations typical of human cancer, suggesting they may be immortalized clones of nonmalignant cells." (PMID 21253487, 2010). "In non-cancer cells such as dermal fibroblasts and primary hepatocytes chronic hypoxia does not change the expression of CCL3/MIP-1α and CCL4/MIP-1β." (PMID 32781743, 2020). "There are no reports on the recruitment of TAM by CCL3 or CCL4; they support the anticancer functions of monocytes, so they will not recruit TAM but will be more responsible for the infiltration of anti-cancer M1 macrophages." (PMID 33076281, 2020). "Although CPXM1, CCL4, ZBTB10 and B3GNT2 have not been reported to be related to the prognosis of ALL, the four genes we screened are all closely related to cancer, and we have reason to believe that they may also be potential genes for predicting the prognosis of ALL." (PMID 36407095, 2022).
bacterial infection (11 papers, 2010 to 2025). "Analysis of proinflammatory cytokines and chemokines at different time points showed significant upregulation of Tnf, Mmp14, Il1b, Il1a, Il17ra, Cxcl1, Cxcl2, Ccrl2, Ccl3, Ccl4, and Ccl9 after bacterial infection." (PMID 41117166, 2025). "Conversely, the downregulation of CCL4 and CCL25 in caspase-1-deficient cells suggests that caspase-1 is essential for maintaining adequate recruitment of macrophages and dendritic cells, which are important for mounting an effective immune response against bacterial infections." (PMID 40137780, 2025). "The cytolytic granules have been shown to contain chemokines such as CCL3, CCL4 and CCL5 in addition to the classical mediators of cytotoxicity (GZMB, PRF1 and GNLY), in both viral and bacterial infections, indicating their role in cytolysis." (PMID 38501302, 2024). "As members of the CC chemokine subfamily, CCL-4 and CCL-5 play important roles in the inflammatory response during a variety of bacterial infections." (PMID 31783919, 2019). "Consistent with this, patients with amputations resulting from combat wounds showed increased serum levels of CCL3 and CCL4 as well as increased CXCL8, CCL3, and CCL4 in the wound effluent due to bacterial infection." (PMID 30340330, 2018).